C9 (complement C9)
Diseases named in the same sentence as C9 in open-access papers (continued):
Sharing a sentence is not in itself a finding about the gene and the disease.
glaucoma (4 papers, 2017 to 2024). Increased pressure in the eyeball due to obstruction of the outflow of aqueous humor. "In the AH of glaucoma patients, complement component C1q, C8 β chain, C9, and V-set immunoglobulin domain-containing protein 4, were measured overexpressed." (PMID 34943212, 2021). "We quantified the majority of key proteins associated with classical complement pathway, such as C1q, C1s, C1r, C4a, C4b, C3, C5, C6, C7, C8a, C8b, C8g and C9, as up-regulated in glaucoma condition for both vitreous and retinal tissues when compared to the controls." (PMID 28978942, 2017).
malaria (4 papers, 2016 to 2025). Malaria is a serious and sometimes fatal disease caused by a parasite that commonly infects a certain type of mosquito which feeds on humans. "Here, we show that oncofoetal chondroitin sulphate, a malignancy‐associated glycosaminoglycan modification, is present on tdEVs and can be targeted by the malaria VAR2CSA protein or C9 antibody." (PMID 40527727, 2025). "It was observed that the levels of Complement C3 and Complement C4-B, Complement C5, Complement C9, Complement factor B and Complement C1q subcomponent subunit C were significantly elevated in malaria plasma MPs compared to controls." (PMID 28352210, 2016).
breast carcinoma (3 papers, 2019 to 2025). "Second, exposure to the SMRwt peptide inhibited mortalin and complement C9 expression in MDA-MB-231, MCF-7 breast cancer cells and K562 leukemia cells as measured by the Western blot analysis." (PMID 31534628, 2019). "Conversely, inflammatory proteins, such as complement C3, complement C9, complement factor B, and complement 4B, were significantly elevated in TNBC patients, suggesting a shift toward a pro-inflammatory HDL-C phenotype in aggressive breast cancer." (PMID 40430118, 2025).
Cognitive impairment (3 papers, 2013 to 2018). Abnormal cognition is characterized by deficits in thinking, reasoning, or remembering. "The cerebellum has been of particular interest because high levels of DPR proteins and RNA foci were found in cerebellar Purkinje and granule cells in C9+ patients, and levels of cerebellar DPR proteins in C9+ ALS were correlated with cognitive impairment." (PMID 30568632, 2018). "Our C9-ALS/FTD zebrafish model is the first to recapitulate the motor deficits, cognitive impairment, muscle atrophy, motor neuron loss and mortality in early adulthood observed in human C9orf72-ALS/FTD." (PMID 30454072, 2018). "Although C9+ ALS patients may have more thalamic atrophy compared to C9– ALS patients with a similar degree of cognitive impairment, the association between thalamic atrophy and cognitive impairment can be seen in FTD patients with other gene mutations and C9– ALS patients with cognitive impairment." (PMID 30568632, 2018). "Although these core genes like C9 and CFI were from Pattern 2 which was related to sensory function, the immunological roles of these genes imply that immune functions could be critical on cognitive impairment by BCCAO." (PMID 23936146, 2013).
esophageal adenocarcinoma (3 papers, 2020 to 2023). A malignant tumor with glandular differentiation arising predominantly from Barrett mucosa in the lower third of the esophagus. "Recently, we reported the release of C9+ EVs by esophageal adenocarcinoma cells as a potential mechanism of the elevated serum C9 glycoform in esophageal cancer." (PMID 37147936, 2023). "Recently our group identified elevated C9 in the serum and tumors of patients with esophageal adenocarcinoma (EAC), a cancer of the gastro-esophageal junction associated with chronic gastro-esophageal reflux (GERD)." (PMID 35345676, 2022). "In agreement with our finding in patient cohorts, a rat model of gastroesophageal reflux showed differential expression of C9 mRNA during progression from the precursor condition Barrett’s esophagus (BE) to EAC." (PMID 35345676, 2022). "We previously reported elevated serum and tissue C9, the terminal complement component, in esophageal adenocarcinoma (EAC) compared to the precursor condition Barrett’s Esophagus (BE) and healthy controls." (PMID 35345676, 2022).
glomerulosclerosis (3 papers, 2021 to 2023). A hardening of the kidney glomerulus caused by scarring of the blood vessels. "Immunohistochemistry showed that complement C9 and ApoE were highly expressed in both KW nodules and solidified glomerulosclerosis compared with class I glomeruli or primary FSGS." (PMID 33633132, 2021). "Proteins of the complement system (complement C3/C9/C8γ) and those involved in lipid metabolism (apolipoprotein [Apo]E) were highly enriched in solidified glomerulosclerosis." (PMID 33633132, 2021). "Our previous study using single-nephron proteomic analysis and immunohistochemical staining suggested complement factors such as C3, C8, and C9 are overactivated in solidified glomerulosclerosis in patients with DN." (PMID 34043214, 2021). "The results of single-nephron proteomic analysis and immunohistochemistry suggested that complement factors C3, C8, and C9 are overactivated in solidified glomerulosclerosis." (PMID 33633132, 2021). "Additionally, single glomerular proteomics, combined with immunohistochemistry, revealed that complement C9 and apolipoprotein E were highly expressed in solidified glomerulosclerosis." (PMID 33633132, 2021). "Moreover, consistent with the results of single glomerular proteomics, the percentage of the glomerular complement C9 and ApoE-positive area was higher in solidified glomerulosclerosis than in KW nodules." (PMID 33633132, 2021).
mastitis (3 papers, 2023 to 2025). Inflammation of breast tissue during lactation or postpartum due to an obstructed duct or infection. "Additionally, some PNAbv regions harbor genes related to mastitis, such as C9, FYB, and MYD88." (PMID 41273432, 2025). "Moreover, when we analyzed introgression in the Nera di Arbus, we found that some of the PNAbv regions harbor QTLs and genes (e.g., C9, FYB, and MYD88) related to somatic cell count and mastitis resistance, traits essential for udder health." (PMID 41273432, 2025).
multiple sclerosis (3 papers, 2022 to 2023). A progressive autoimmune disorder affecting the central nervous system resulting in demyelination. "Compared to controls, multiple sclerosis patients had a higher Body-Mass-Index, Protein-C and activated-C9; and a lower activated-C4." (PMID 37583699, 2023).
non-small cell lung carcinoma (3 papers, 2018 to 2022). A group of at least three distinct histological types of lung cancer, including non-small cell squamous cell carcinoma, adenocarcinoma, and large cell carcinoma. "Furthermore, the restrained expression of C9 in tumor-associated macrophages promotes non-small cell lung cancer progression." (PMID 35982973, 2022). "C9 played a crucial role in CDC-mediated tumoricidal activity, and hypoxia could downregulate C9 in TAMs, promoting non-small cell lung cancer progression." (PMID 31787848, 2019).
proteinopathies (3 papers, 2022 to 2025). "In our cohort with a larger data set, especially the C9-HRE group was associated with low total TDP-43 levels, which might support the previous hypothesis that in TDP-43-positive proteinopathies, the p-TDP-43/TDP-43 ratio could be imbalanced." (PMID 36217158, 2022). "Longitudinal measurements in asymptomatic C9 carriers will be particularly interesting as it may be possible to track the development of TDP‐43 pathology and identify triggers of TDP‐43 proteinopathy." (PMID 39913612, 2025).
Sepsis (3 papers, 2019 to 2025). Sepsis is defined as life-threatening organ dysfunction caused by a dysregulated host response to infection. "Serum sCD59, inhibiting the formation of C5b-9 through preventing the incorporation and polymerization of C9 on cell membranes, was elevated in patients with sepsis, severe acute pancreatitis, acute myocardial infarction, and lung transplantation." (PMID 36732841, 2023).
acute kidney injury (2 papers, 2014 to 2019). Sudden and sustained deterioration of the kidney function characterized by decreased glomerular filtration rate, increased serum creatinine or oliguria. "Studies in complement-deficient mice have shown that mice are protected from renal failure after ischemia/reperfusion (I/R), and that generation of the anaphylatoxin C5a and the membrane attack complex (C5b-C9 or MAC) may contribute to the pathogenesis of ischemic AKI." (PMID 24967359, 2014). "Another study showed immunostaining for C1q, C3c, C4c,C5, C9, and factor H were found in the kidney cortex and medulla of sheep with acute kidney injury." (PMID 31338070, 2019).
Allergy (2 papers, 2020 to 2026). An allergy is an immune response or reaction to substances that are usually not harmful. "CTSC1 and C9 regulate innate immunity, neutrophil activation and inflammation in the tears, leading to an increase in transport of allergy mediators to the site of allergen exposure to clear away irritation-triggering allergy peptides on the ocular surface." (PMID 41596322, 2026). "C2, C9, IL5, SIGLEC15, and IL1RAP are examples of molecules with roles in immunity, inflammation and allergy that demonstrate seasonal effects." (PMID 33004787, 2020).
amyloid (2 papers, 2021 to 2023). "Based on this observation they systematically explored the presence of Complement C9 in 118 tissue samples from 18 different tissue types with amyloid deposits." (PMID 35008745, 2021).
aneurysm (2 papers, 2021). Bulging or ballooning in an area of an artery secondary to arterial wall weakening. "We also found lower deposition of complement C3 (activated by classical, alternative and lectin pathways) and C9 (member of membrane attack complex), which are critical mediators of aneurysm." (PMID 34323424, 2021).
Arthritis (2 papers, 2013 to 2022). Inflammation of a joint. "Purified human C9 antibody, when used prophylactically in an adult wild-type mouse model of CHIKV disease, completely protected against viremia and arthritis." (PMID 24069479, 2013). "In contrast to control mice, mice pretreated with C9 antibody had no detectable CHIKV viremia or arthritis." (PMID 24069479, 2013).
asthma (2 papers, 2023 to 2024). "Membrane attack complex components (C6, C7, C8, C9) were found to be significantly elevated or upregulated in different samples in asthma compared to control groups, but the results from different studies were consistent only for the elevation of C9." (PMID 38892755, 2024).
bacteremia (2 papers, 2022 to 2025). "C9 is a component of the membrane attack complex (MAC) and low levels of C9 were found to be associated with septic shock in patients with Gam-negative bacteremia." (PMID 40898225, 2025). "Indeed, a recent prospective study evaluated complement levels in bacteremia patients, and hypothesized the measurement of C3, C4 and C9 levels may help stratify Gram-negative bacteremia patients at increased risk for mortality." (PMID 36261775, 2022).
Colon Cancer (2 papers, 2015 to 2020). "In addition, previous studies have reported that prostate cancer, colon cancer, and squamous cell lung cancer may secrete common plasma proteins such as zinc-alpha-2-glycoprotein and complement C9." (PMID 26425554, 2015).
coronary atherosclerosis (2 papers, 2020 to 2021). Atherosclerosis of the coronary vasculature. "Proteomic studies of the blood of patients with coronary atherosclerosis showed an increase in the content of components of the complement system C3 (chain B), C4, C9 and a decrease in the level of the complement component C3 (chain C)." (PMID 34948066, 2021). "Proteome profiling of serum revealed a change in the content of kininogen, hemopexin, transthyretin, retinol-binding protein, and proteins of the complement system (C9, and C3) in coronary atherosclerosis." (PMID 33033454, 2020).
deficiencies (2 papers, 2014 to 2020). "However, unlike C9 deficiency (the most common TCC deficiency in the oriental populations), C6 deficiencies have seldomly been reported in Asians, especially in Han Chinese." (PMID 32670577, 2020).
dementia (2 papers, 2016 to 2020). Loss of intellectual abilities interfering with an individual's social and occupational functions. "None of the presymptomatic C9+ carriers developed ALS or dementia during follow-up scanning." (PMID 32769055, 2020). "However, even C9 + ALS patients without dementia had regions of thinning compared to sporadic ALS patients." (PMID 27995069, 2016).
dermatomyositis (2 papers, 2022 to 2025). Dermatomyositis (DM) is a type of idiopathic inflammatory myopathy characterized by evocative skin lesions and symmetrical proximal muscle weakness. "C9 deficiency has been reported in limited patients with dermatomyositis and susceptibility to various infections." (PMID 39992598, 2025). "Although MAC formation is a typical feature in DM, the description of typical dermatomyositis in patients with hereditary deficiencies of complement factor 9 (C9) illustrates that DM may occur without the formation of C5b-9/MAC." (PMID 35457124, 2022).
dysplasia (2 papers, 2022 to 2024). A usually neoplastic transformation of the cell, associated with altered architectural tissue patterns. "Increased C9 and C5b-9 staining were observed in the sequence normal squamous epithelium, BE, low- and high-grade dysplasia, EAC." (PMID 35345676, 2022).
Huntington disease (2 papers, 2018 to 2025). Huntington disease (HD) is a rare neurodegenerative disorder of the central nervous system characterized by unwanted choreatic movements, behavioral and psychiatric disturbances and dementia. "Further complicating matters, the C9 expansion has been associated with scarce disease incidence in a wide spectrum of neurodegenerative and psychiatric conditions, including Huntington’s Disease, Parkinson’s Disease, and Schizophrenia." (PMID 30003873, 2018).
leprosy (2 papers, 2015 to 2017). Leprosy is a chronic infectious disease affecting primarily the skin and peripheral nervous system. "To determine the extent of MAC and C3d deposition in skin biopsies of reaction leprosy patients we performed immunohistochemistry for C3d and C9 detecting MAC." (PMID 28505186, 2017).
meningitis (2 papers, 2016 to 2023). A disorder characterized by acute inflammation of the meninges of the brain and/or spinal cord. "One patient carried a heterozygous, stop-gain variant in the C9 gene, which has been associated with recurrent meningitis." (PMID 27703454, 2016). "C9 ADIA, LAIR1, and ADIB, all of which are associated with complement and coagulation cascades, were profoundly overexpressed in the CSF samples of patients with HEV-positive meningitis." (PMID 37153144, 2023).
neuroblastoma (2 papers, 2015 to 2023). Neuroblastoma (NB) is the most common solid, extracranial childhood tumor. "There was constitutive expression of complement factor B, C3, C5 and C9 in SH-SY5Y neuroblastoma cell lines stably expressing the NOTCH3 receptor." (PMID 37158955, 2023). "However, it has been shown that the protein IL6 is able to stimulate C9 mRNA expression in post-mortem human astrocytes and neuroblastoma cells, showing a metabolic link between the two proteins in the cells of the nervous system." (PMID 26626881, 2015).
Obesity (2 papers, 2022 to 2025). Accumulation of substantial excess body fat. "For instance, complement component C9, the root classifier in the obesity model, is a terminal effector of the membrane attack complex and has been implicated in metabolic inflammation and vascular injury." (PMID 40981199, 2025). "Collectively, the reciprocal shift from protective proteins like TTR, APOD, and PRDX2 to pro-inflammatory mediators such as CRP and C9 highlights a coordinated reprogramming of adiposome cargo in obesity." (PMID 40981199, 2025). "Key predictive proteins such as C9, TTR, CRP, and S100A9 are not only differentially abundant in obesity but also implicated in the pathogenesis of endothelial dysfunction, systemic inflammation, and insulin resistance, further validating their mechanistic relevance." (PMID 40981199, 2025). "Both drugs have proven to be effective in reducing inflammation through various pathways: they reduced CRP levels in patients with obesity, while colchicine was also effective in reducing IL‐6, IL‐16, resistin, complement proteins C5a and C9, and the activity of the COX‐2 enzyme." (PMID 35837843, 2022). "The patients with obesity taking colchicine had lower levels of C5a and C9 as compared to patients with obesity under placebo, and complement activation was observed in the endothelium of the subcutaneous adipose tissue associated with the presence of the virus." (PMID 35837843, 2022). "Among the proteins upregulated in obesity, CRP, C9, and APOC1 not only showed elevated abundance but also demonstrated strong, consistent links across metabolic, vascular, and inflammatory domains." (PMID 40981199, 2025). "Similarly, the Complement Activation Network, characterized by increased C9 and CRP and decreased C1QB, aligned with the chronic low-grade inflammation observed in obesity." (PMID 40981199, 2025).
periodontitis (2 papers, 2020 to 2021). An acute or chronic inflammatory process that affects the tissues that surround and support the teeth. "The low abundance of the pro-inflammatory molecule PTX3, an acute phase protein increased during aggressive periodontitis, or the complement component C9 is in agreement with the histological and clinical findings reported." (PMID 34777248, 2021).
preeclampsia (2 papers, 2017 to 2021). Preeclampsia is a hypertensive disorder of pregnancy that is characterized by new-onset hypertension with proteinuria presenting after 20 weeks of gestation, and depending on mild or severe forms may initially present with severe headache, visual disturbances, and hyperreflexia. "After the first trimester of gestation, the serum level of C9 is downregulated in women with normal pregnancy compared with females with preeclampsia." (PMID 34827915, 2021).
psoriasis (2 papers, 2018 to 2024). An autoimmune condition characterized by red, well-delineated plaques with silvery scales that are usually on the extensor surfaces and scalp. "By comparing PsA plasma to psoriasis plasma, only C9 levels were significantly higher in psoriasis than in PsA, p = 0.02." (PMID 30279686, 2018). "Since we observed presence of IgG in the PsA synovial compartment and antibody reactivity to both native and citrullinated LL37, we assessed the content of C5a, C9, and GM-CSF in SF of PsA and control OA patients and, for comparison, in plasma of PsA and psoriasis patients." (PMID 30279686, 2018). "Activated complement (C5a, C9), GM-CSF and IFN-I are up-regulated in PsA and not OA synovia and in PsA and psoriasis plasma but not in HD." (PMID 30279686, 2018).
psychosis (2 papers, 2021 to 2022). "Interestingly, the decrease in terminal complement components C9 and C8 in mice is mirrored in a recent study showing decreased TCC in first episode psychosis (FEP) compared to normal controls." (PMID 30635638, 2021).
schizophrenia (2 papers, 2018 to 2022). A major psychotic disorder characterized by abnormalities in the perception or expression of reality. "Accompanying the metabolic disruption identified in patients with schizophrenia was an increase in several complement effector proteins, including C4a/b, C5, C6, C8a, and C9." (PMID 34741130, 2022).
vasculitis (2 papers, 2022 to 2023). "Overall, the high fold increases in MASP1 and CFB together with decreased SERPINA5 and increased C9 suggest the role of the lectin and alternate complement pathway in this form of vasculitis." (PMID 37238213, 2023). "It has also been demonstrated that plasma from Vasculitis patients has significantly more C3- and C9-positive endothelial MVs than controls." (PMID 39086962, 2022).